MPV17L (MPV17 mitochondrial inner membrane protein like)
Description:
[Isoform 1]: Participates in reactive oxygen species metabolism by up- or down-regulation of the genes of antioxidant enzymes. Protective against the mitochondrial apoptotic cascade.
Synonyms: M-LPH; FLJ39599; M-LPH1; M-LPH2; MPV17L1; MLPH1; MLPH2
Tractability: Antibody: UniProt predicts a signal peptide or a membrane-spanning region.
Gene: Protein-coding gene on chromosome 16 (15,395,754 to 15,413,271, forward strand). Ensembl gene ENSG00000156968.
Subcellular location: Peroxisome membrane (Isoform 1)
Subcellular location (Human Protein Atlas): Vesicles
Gene Ontology:
Biological process: negative regulation of hydrogen peroxide biosynthetic process; negative regulation of mitochondrial outer membrane permeabilization involved in apoptotic signaling pathway
Cellular component: peroxisomal membrane; mitochondrion; membrane
Genetic constraint (gnomAD): Loss-of-function variants: 19 observed, 16.01 expected, observed/expected ratio (o/e) 1.19, 90% interval 0.83 to 1.71. The upper end of that interval is the gene's LOEUF score, 1.71, which puts it in group 6 of 6, group 1 being the genes least tolerant of losing a copy. Missense variants: 230 observed, 180.77 expected, observed/expected ratio (o/e) 1.27, 90% interval 1.14 to 1.42. Synonymous variants: 93 observed, 71.64 expected, observed/expected ratio (o/e) 1.3, 90% interval 1.1 to 1.54.
Homologues: Orthologues: chimpanzee MPV17L (91% identical), dog MPV17L (80% identical), mouse Mpv17l (78% identical), rabbit MPV17L (77% identical), guinea pig MPV17L (77% identical), pig MPV17L (73% identical), rat Mpv17l (71% identical), zebrafish mpv17l (45% identical), Drosophila melanogaster CG14777 (25% identical), Drosophila melanogaster plh (21% identical), Drosophila melanogaster CG14778 (20% identical). Paralogues in human: MPV17 (24% identical), MPV17L2 (23% identical), PXMP2 (21% identical).
Diseases named in the same sentence as MPV17L in open-access papers:
MPV17L is named in the same sentence as 11 diseases in open-access papers, as found by Europe PMC text mining. Sharing a sentence is not in itself a finding about the gene and the disease. The quoted sentences say what the papers report.
cardiac hypertrophy (1 paper, 2023). "Here, we report another phenotype of M-LP/Mpv17L-KO mice, afferent cardiac hypertrophy, and discuss the effects of M-LP/Mpv17L deficiency on cardiac growth." (PMID 37851308, 2023). "Taken together, these findings indicate that M-LP/Mpv17L is one of the PDEs actively functioning in the heart and that deficiency of M-LP/Mpv17L in mice promotes physiological cardiac hypertrophy." (PMID 37851308, 2023).
diabetes (1 paper, 2024). "Meanwhile, to examine whether the onset of diabetes caused by STZ administration affected the expression of M-LP/Mpv17L, we analyzed its expression in the pancreas of the WT-control and the WT-STZ groups at 13 days after STZ treatment." (PMID 39085522, 2024). "In addition, this study showed that M-LP/Mpv17L expression was down-regulated in the pancreas of mice with STZ-induced diabetes." (PMID 39085522, 2024).
glomerulosclerosis (1 paper, 2022). A hardening of the kidney glomerulus caused by scarring of the blood vessels. "Mpv17l was also linked to the development of early-onset glomerulosclerosis and could modulate antioxidant enzyme expression." (PMID 35432190, 2022).
kidney damage (1 paper, 2015). "In the process of kidney fibrogenesis, miR-21 upregulates ROS level by repressing the mitochondrial inhibitor of ROS generation Mpv17l, and enhances oxidative kidney damage." (PMID 25925316, 2015).
lung diseases (1 paper, 2022). "For the majority of genes such as Elac2, Csnk1a1, Eif3a, Eif4g2, Tmed2 and Mpv17l, a role in the pathogenesis of lung diseases was indicated by previous studies, although their functions in the neonatal lung remain unexplored." (PMID 36271035, 2022).
schizophrenia (1 paper, 2009). A major psychotic disorder characterized by abnormalities in the perception or expression of reality. "All three deletions included the region chr16:15387380–16198600 (and the genes MPV17L, c16orf45, KIAA0430, NDE1, MYH11, KIAA0866, c16orf63, ABCC1 and MRP6/AbCC6) indicating that a large deletion of this region may be a recurrent schizophrenia risk factor." (PMID 19197363, 2009).
MPV17L also shares sentences with these, for which no sentence is quoted: Hepatoma (1 paper); Hyperglycemia (1); mitochondrial DNA depletion syndrome (1); type 1 diabetes (1); type 2 diabetes (1).